CETP (cholesteryl ester transfer protein)
Diseases named in the same sentence as CETP in open-access papers (continued):
Sharing a sentence is not in itself a finding about the gene and the disease.
hyperlipidemia (continued). "The moderate CETPi group, as shown in this study, did not modify postprandial lipemia, probably due to the CETP dependence on the TRL pool size shown." (PMID 21609439, 2011). "Our model to estimate CETP-mediated TG redistribution using only the ratios TG/(TG + CE) and surfaces of TRL, IDL, LDL, and HDL is applicable in postprandial lipemia as well—with or without discrimination of TRL into CM and VLDL + CMR fraction (d > 1.006)." (PMID 40562102, 2025).
Sepsis (37 papers, 2012 to 2025). Sepsis is defined as life-threatening organ dysfunction caused by a dysregulated host response to infection. "Gain-of-function genetic variants in CETP are associated with a large decline in HDL-C during sepsis and with increased risk of death." (PMID 38646937, 2024). "In humans, pneumonia is the leading cause of sepsis, and we therefore tested the effect of CETP inhibition in a mouse model of lower respiratory tract infection." (PMID 38646937, 2024). "Previous research has indicated that individuals carrying the A allele of the CETP gene variant (rs1800777-A) experience reduced HDL-C levels during sepsis." (PMID 37621565, 2023). "Its therapeutic potential is also strengthened by the observation that a CETP gain-of-function genetic variant is associated with increased sepsis mortality." (PMID 38015312, 2023). "One crucial point is that torcetrapib, another CETP inhibitor, was discovered to increase the risk of cardiovascular mortality, cancer, and sepsis." (PMID 37621565, 2023). "A CETP (cholesteryl ester transfer protein) gain-of-function variant was associated with significant reductions in HDL-C levels during sepsis, and increased risk of mortality." (PMID 35843172, 2022). "In agreement with this, CETP gain-of-function mutations in humans were associated with increased mortality due to sepsis, while reduced CETP function was associated with increased survival." (PMID 34638523, 2021). "Most importantly, the association of CETP variant rs1800777 (allele A) and increased risk for sepsis-associated AKI was replicated in the Validation Cohort." (PMID 30425299, 2018). "Patients carrying the CETP variant rs1800777 (allele A) had significantly increased frequency of sepsis-associated AKI KDIGO stages 2 and 3 compared to WT patients (51.6% vs. 31.1%, P = 0.030)." (PMID 30425299, 2018). "In our multiple logistic regression model, the presence of the CETP variant rs1800777 (allele A) variant was independently associated with higher risk of development of sepsis-associated AKI stages 2 and 3 (OR = 8.28, P = 0.013)." (PMID 30425299, 2018). "A higher proportion of patients who carried the minor allele (allele A) of the CETP variant rs1800777 variant developed clinically significant sepsis-associated AKI in comparison to the WT group (70.0% vs. 27.9%, P = 0.009)." (PMID 30425299, 2018). "Only the minor allele of the CETP variant rs1800777 (allele A) showed a significant association with HDL-C levels at sepsis admission after Benjamini-Hochberg correction (P = 0.042)." (PMID 30425299, 2018). "Future studies evaluating the safety and efficacy of CETP inhibitors in sepsis sepsis-associated AKI are warranted." (PMID 30425299, 2018). "Patients who carried the minor allele of CETP variant rs1800777 had significantly lower median HDL-C levels at sepsis admission in comparison to the WT group (17.40 mg/dL vs. 32.87 mg/dL, P = 0.002)." (PMID 30425299, 2018). "Preclinical studies are necessary before future clinical trials of CETP inhibition for the treatment/prevention of sepsis-associated AKI." (PMID 30425299, 2018). "In addition, experimental and human studies have implicated CETP in protection against acute inflammatory conditions, such as LPS-induced mortality in mice and sepsis-related mortality in hospitalized patients." (PMID 38966642, 2024). "Reduction in plasma CETP on day three of sepsis has been linked to mortality." (PMID 37621565, 2023). "Moreover, polymorphisms in HDL metabolism genes such as rs1800777 (allele A) in the CETP gene, were strongly associated with an increased risk of kidney injury during sepsis." (PMID 36589822, 2022). "Gain-of-function variants in cholesterol ester transfer protein (CETP) in human studies have been associated with increased mortality from sepsis, and inhibition of CETP in humanized mouse models has been associated with preserved HDL levels and increased survival." (PMID 33920038, 2021).
Sepsis (continued). "The CETP expression in mice was associated with significantly lower basal plasma lipid levels and with higher mortality rates in both models of endotoxemia and sepsis." (PMID 33500240, 2021). "In fact, pharmacological inhibition of CETP has been linked to increased sepsis and mortality." (PMID 33102504, 2020). "Although not proven experimentally in this study, we can speculate how CETP variant rs1800777 (allele A) might cause sepsis-associated AKI." (PMID 30425299, 2018). "The major new findings in this study are that the CETP variant rs1800777 (allele A) was associated with a much lower plasma HDL-C levels during sepsis, a great increment in CETP mass, and a doubling of the risk for the development of clinically significant sepsis-associated AKI." (PMID 30425299, 2018). "Our findings present a hypothesis for future randomized controlled trials with CETP inhibitors in sepsis-associated AKI." (PMID 30425299, 2018). "CETP genotype may represent a novel tool to risk stratify patients with sepsis." (PMID 30736368, 2019). "CETP genotype may identify patients at high-risk of sepsis-associated AKI." (PMID 30425299, 2018). "CETP is responsible for the transport of cholesteryl esters in the body, and sepsis can lead to alterations in CETP expression, subsequently affecting cholesterol transport and CE synthesis." (PMID 41346598, 2025). "To further investigate the translational potential of CETP inhibition, we tested the effect of acute CETPi treatment administered after the onset of S. pneumoniae–induced sepsis in female APOA1.CETP mice." (PMID 38646937, 2024). "The decreased CETP activity observed in sepsis is regarded as a compensatory mechanism preventing systemic endotoxemia." (PMID 38603717, 2024). "Previously, we demonstrated a protective role of CETP inhibition in an intraabdominal model of sepsis." (PMID 38646937, 2024). "CETP inhibition improves Streptococcus pneumoniae–induced sepsis mortality in APOE*3-Leiden.CETP mice." (PMID 38646937, 2024). "In contrast gain-of-function mutations affecting CETP, leading to decreased HDL-C, are associated with increased risk of mortality due to sepsis." (PMID 38290288, 2024). "Here we investigated the effects and cellular mechanisms of CETP inhibition on the immune response in mouse models of S. pneumoniae–induced sepsis." (PMID 38646937, 2024). "CETP inhibition enhances macrophage infiltration to the site of infection and monocyte activation at different stages of sepsis." (PMID 38646937, 2024). "For instance, in mice with polymicrobial sepsis, CETP inhibition helped maintain plasma HDL-C and apoA1 levels, resulting in higher survival rates compared with the placebo." (PMID 39057711, 2024). "The cholesteryl ester transfer protein inhibitor anacetrapib reduces mortality from Streptococcus pneumoniae-induced sepsis in mice by enhancing monocyte activation, improving bacterial clearance, and reducing organ injury." (PMID 38646937, 2024). "Overall, we found that HMGCR and CETP inhibitors had positive effects in the treatment of total sepsis." (PMID 37621565, 2023). "The indirect impact of ApoA-I explained over 50% of the curative effects of CETP inhibitors in sepsis." (PMID 37621565, 2023). "In agreement, other studies have reported lower plasma concentrations of TNF-α and IL-6 in transgenic mice expressing CETP compared to wild-types following LPS stimulation or sepsis." (PMID 37892238, 2023). "To better understand the therapeutic effects of CETP inhibitors on sepsis, we analyzed ApoA-I as a mediator." (PMID 37621565, 2023). "Transgenic mice expressing physiological concentrations of CETP exhibited reduced plasma inflammatory cytokines and lower mortality when exposed to bacterial lipopolysaccharide (LPS) or after polymicrobial sepsis induced by cecal ligation and puncture." (PMID 36139808, 2022).
Sepsis (continued). "Recent work showed that a gain-of-function variant in CETP gene was associated with lower plasma HDL cholesterol levels, more pronounced proinflammatory cytokines release, and greater risk of sepsis-associated acute kidney injury." (PMID 33500240, 2021). "In patients with sepsis, a pronounced reduction of CETP plasma concentration on the first day of admission was associated with a higher mortality rate." (PMID 33500240, 2021). "CETP-mediated HDL-C drop in septic patients was later shown to play a causal and deleterious role in survival from sepsis." (PMID 33500240, 2021). "In order to get more insights into the possible role of CETP on LPS detoxification and its consequences on sepsis outcome in a model of polymicrobial infection, we applied the CLP protocol to CETPTg and WT mice." (PMID 33500240, 2021). "CETP is involved in the inflammatory response in mice expressing the human CETP gene (huCETP), which is more resistant to endotoxemia and experimental sepsis than in wild type mice." (PMID 34367144, 2021). "In previous studies, we demonstrated a greater survival rate in human CETP transgenic mice than in WT mice with experimental sepsis." (PMID 34367144, 2021). "In this sense, it was recently suggested that CETP inhibitors be redirected to the treatment of sepsis." (PMID 34367144, 2021). "It is in line with expected outcome of CETP expression, and CETP activity remained stable along the sepsis episode." (PMID 33500240, 2021). "Since a gain-of-function mutation in cholesteryl ester transfer protein (CETP) is associated with lower HDL levels and higher mortality in sepsis, increasing HDL levels using CETP inhibitors seems to be another promising strategy." (PMID 33039713, 2020). "Interestingly, a recent study has shown that variations in genes involved in HDL metabolism could contribute to changes in HDL-C level; a rare missense variant in CETP (rs1800777-A) was thus associated with significant reductions in HDL-C concentration during sepsis." (PMID 31197574, 2019). "Our findings strongly support the importance of the CETP gene as a modulator of HDL-C levels in sepsis." (PMID 30425299, 2018). "This raises the possibility for new therapeutic tools in sepsis while suggesting that lowering CETP by pharmacological inhibitors should be inconvenient in the context of sepsis and infectious diseases." (PMID 27293313, 2016). "CETP mice showed greater resistance to CLP induced sepsis, with a survival rate of 93.3% versus 60% of the WT group, confirming previous findings in the experimental model of endotoxemia." (PMID 27293313, 2016). "Human CETP transgenic mice were compared to control mice (wild type, WT) after polymicrobial sepsis induced by cecal ligation and puncture (CLP), aiming at investigating their survival rate and inflammatory profiles." (PMID 27293313, 2016). "A potential anti-inflammatory role for CETP was demonstrated previously wherein the induction of acute inflammation produced lower mortality due to sepsis and lower cytokine circulation in mice that express human CETP." (PMID 23039379, 2012). "Similarly, reduced CETP levels, known to correlate with worse outcomes in adult sepsis, suggest an impaired ability to manage lipid trafficking during the systemic inflammatory response." (PMID 40927580, 2025). "Therefore, further studies are needed to elucidate the role of CE in sepsis and its relationship with CETP." (PMID 41346598, 2025). "Our findings suggest that CETP inhibition may have a dual effect on macrophage function during sepsis." (PMID 38646937, 2024). "Mounting evidence suggests that inhibiting CETP may also be beneficial in severe inflammatory states, such as sepsis." (PMID 39057711, 2024). "CETP concentrations decline during severe sepsis, which may represent a physiological response to preserve the beneficial innate immune function of HDL during sepsis." (PMID 38646937, 2024).
Sepsis (continued). "In addition, CETP inhibition promoted monocyte activation in the blood prior to the onset of sepsis, resulting in accelerated macrophage recruitment to the lung and liver." (PMID 38646937, 2024). "A CETP inhibitor was hypothesized to attenuate HDL-C loss and help to preserve functionality of HDL particles during sepsis." (PMID 38603717, 2024). "Specifically, our results indicate that CETP inhibition promotes monocyte recruitment in the blood and proinflammatory macrophage recruitment into the lungs, supporting the host immune response during the early phase of sepsis." (PMID 38646937, 2024). "CETP inhibition improves S. pneumoniae–induced sepsis mortality in APOA1.CETP mice." (PMID 38646937, 2024). "Collectively, these results suggest that CETP inhibition promotes proinflammatory macrophage infiltration into the lung and macrophage activation to support the host immune response at the early phase of sepsis." (PMID 38646937, 2024). "Recent studies have revealed that an inhibitory variant of the human cholesteryl ester transfer protein (CETP) gene is associated with an increase in the plasma HDL-C concentration and better sepsis outcome, whereas a gain-of-function variant of this gene is associated with the opposite effect." (PMID 38603717, 2024). "This suggests that CETP inhibition may prevent excessive inflammatory response–induced organ damage or may be a result of lower bacterial burden in the later stages of sepsis." (PMID 38646937, 2024). "Whole-body CETP expression protects mice from mortality in sepsis models." (PMID 37892238, 2023). "In addition, CETP improves the anti‐inflammatory effects of HDL via activation of PONs, S1P, and ApoA1, since activation of CETP reduces sepsis‐induced inflammation, increases HDL, and improves survival in experimental studies." (PMID 37249296, 2023). "ApoA-I was also found to explain half of the effects of CETP inhibitors on sepsis." (PMID 37621565, 2023). "No human data on CETP activity is available, but a CETP gain-of-function genetic variant was associated with increased sepsis mortality." (PMID 38015312, 2023). "Additionally, the survival rate of patients with sepsis correlates with the plasma CETP concentration." (PMID 37892238, 2023). "In drug-MR, HMGCR and CETP inhibitors showed therapeutic value for sepsis." (PMID 37621565, 2023). "In addition, patients’ plasma CETP levels were correlated with sepsis survival, supporting findings of increased deaths by infections and sepsis in the CETP inhibitor Torcetrapib trial." (PMID 36139808, 2022). "Additionally, a positive correlation between plasma CETP concentration and sepsis survival rate was reported." (PMID 34367144, 2021). "Furthermore, higher CETP expression in animal models lead to higher mortality in sepsis or endotoxemia." (PMID 35071235, 2021). "Although we could show that CETP is able to alter LPS transport and excretion in a model of isolated endotoxemia, the contribution of this phenomenon to the deleterious effect of CETP in our sepsis model seems to be modest." (PMID 33500240, 2021). "In addition, carriers of a rare variant in CETP have greater CETP activity and decreased HDL levels along with increased sepsis mortality." (PMID 34087197, 2021). "CETP along with lipoprotein acceptors, previously recognized key vehicles for the transport of LPS, plays a fundamental role in the initial reversible phase of sepsis and in the regulation of the inflammatory response triggered by LPS in macrophages." (PMID 34367144, 2021). "Taken together, these data provide evidence that increased mortality and altered inflammatory response in CETPTg mice with endotoxemia or sepsis result from a general reduction in plasma lipid pool as a result from increased CETP-mediated lipoprotein remodeling and/or clearance." (PMID 33500240, 2021).